RN7SL735P (RNA, 7SL, cytoplasmic 735, pseudogene)
Gene: Miscellaneous RNA gene on chromosome 17 (66,364,029 to 66,364,320, forward strand). Ensembl gene ENSG00000244044.
Homologues: Orthologues: chimpanzee Metazoa_SRP (99% identical), macaque Metazoa_SRP (95% identical). Paralogues in human: RN7SL2 (85% identical), RN7SL1 (85% identical), RN7SL3 (84% identical), RN7SL230P (82% identical), RN7SL45P (82% identical), RN7SL589P (82% identical), RN7SL665P (82% identical), RN7SL186P (81% identical), RN7SL300P (81% identical), RN7SL451P (81% identical), RN7SL479P (81% identical), RN7SL597P (81% identical), and 703 more.